ATM (ATM serine/threonine kinase)
Diseases named in the same sentence as ATM in open-access papers (continued):
Sharing a sentence is not in itself a finding about the gene and the disease.
gastric cancer (continued). "In line with our findings, brain tumors have previously been reported in gastric cancer families with causative germline alterations in CDH1 and other (suspected) tumor suppressor genes, e.g. ATM, CTNNA1, and SDHB." (PMID 33929593, 2021). "Taken together, these findings suggest that both DNMT3A downregulation and ATM upregulation are likely to produce better overall survival outcomes for gastric cancer patients." (PMID 34503060, 2021). "Enhanced miR-203 also inhibited ATM activity and suppressed the ATM-Snail pathway, increasing E-cadherin, and thereby preventing the migration and invasion of gastric cancer cells." (PMID 32182776, 2020). "We provide a novel molecular mechanism for the negative regulation of ARID1A by β-TRCP and ATM in gastric cancer cells in response to DNA damage insult." (PMID 31210753, 2019). "Our studies provide a novel molecular mechanism for the negative regulation of ARID1A by β-TRCP and ATM in DNA damaged gastric cancer cells." (PMID 31210753, 2019). "Recent pre-clinical and clinical studies explored the applicability of olaparib synthetic lethality to cancers with disrupted ATM protein expression, specifically gastric cancer and mantle cell lymphoma (MCL)." (PMID 26610585, 2015). "Stomach cancer has a relatively high rate of rare germline truncations, in large part due to frequent PALB2 and ATM mutations." (PMID 26689913, 2015). "It is reported that ATM deficiency sensitizes cells to the growth-inhibitory effects of PARP inhibitor, olaparib, in gastric cancer cells with reduced ATM expression." (PMID 24324828, 2013). "Among 10 human gastric cancer cell lines, SNU-1 and SNU-638 were characterized as MSI positive, ATM gene mutations positive and ATM loss by IHC." (PMID 24324828, 2013). "Gastric cancer cells may maintain intracellular levels of miR-181a-5p and suppress ATM expression by secreting CCAT1 into EVs." (PMID 40045434, 2025). "Familial early-onset gastric cancer is an unusual presentation for ATM-related malignancies." (PMID 37509701, 2023). "For example, ATR is synthetic lethal with the closely related PIKK family kinase ATM, suggesting ATRi could serve some utility in the treatment of cancers, such as gastric cancer, where ATM is defective." (PMID 35567571, 2022). "Furthermore, ATRi sensitivity has been seen in an ATM-defective gastric cancer tumor cell line and in organoid models of gastric cancer." (PMID 36273494, 2022). "Some studies have considered the efficacy of Olaparib in ATM-deficient leukemic cells from patients with leukemia or in patients with gastric cancer, but no studies in BC tumor cells have yet been performed." (PMID 34068084, 2021). "Notably, four gene-disease associations, namely, ATM-gastric cancer, CHEK2-gastric cancer, CHEK2-kidney cancer, and CHEK2-thyroid cancer, were verified by NLP literature review alone." (PMID 33959510, 2021). "To investigate the distribution of ATM protein and m6A reader proteins during the DNA damage, we irradiated SGC7901 gastric cancer cells with ionizing radiation (4Gy) for 30 min, and found that ionizing radiation-induced DNA damage resulted in increased expression of ATM, p-ATM, and H2A.X." (PMID 34729106, 2021). "We also observed biallelic inactivation of ATM in tumors of two gastric cancer patients." (PMID 26506520, 2015).
gastric cancer (continued). "The telomeric protein TRF2, involving in telomeric and extratelomeric DNA damage response, has been previously reported to facilitate multidrug resistance (MDR) in gastric cancer cells by interfering ATM-dependent DNA damage response induced by anticancer drugs." (PMID 25821946, 2015). "Microsatellite instability status and ATM gene profiles of human gastric cancer cell lines." (PMID 24324828, 2013). "The absence of mutations in other DDR-related genes such as ataxia-telangiectasia mutated (ATM), BRCA1, mutL homolog 3 (hMLH3), and Nijmegen breakage syndrome protein 1 (NBS1) suggested a selective vulnerability of the ATR-CHK1 axis in MSI-high gastric cancers." (PMID 40869030, 2025). "One study demonstrated that the ATR inhibitor AZD6738 induces a synthetic lethal phenotype in ATM‐deficient, but not ATM‐proficient, gastric cancer cells, and in vivo tumor growth of ATM‐deficient gastric cell xenografts was effectively controlled by treatment with AZD6738 compared with control." (PMID 30714316, 2019). "ATM is a well-known tumor suppressor but not a known predisposition gene for gastric cancer." (PMID 26506520, 2015). "Inactivation of the ATM gene may be a frequent event in the development of human gastric cancer (GC); however, the events related to the loss of ATM expression in GC could not be explained by the low prevalence of ATM mutation." (PMID 24324828, 2013). "DNA damage-induced ATM activation promotes β-TRCP-mediated ubiquitination and destruction of ARID1A in gastric cancer cells, thereby exacerbating the development of gastric cancer." (PMID 36035159, 2022).
gastric cancer (continued). "This analysis indicated that short periods of M4344 treatment were sufficient to elicit antitumor gastric cancer PDX responses, especially in PDX with either ARID1A or ATM defects." (PMID 36273494, 2022). "Western blot analysis indicated that DNA-PKcs, ATR, Phospho-ATR, ATM, Phospho-ATM, γH2AX, and H2AX were upregulated in oxaliplatin-resistant gastric cancer cells, indicating that DNA damage repair response was activated in SGC-7901-R and KATO III-R cells." (PMID 33462197, 2021). "So far, the basic research about stomach cancer has not involved PP2Acα/PPP2CA except that PP2Acα plays an antineoplastic role through the ATM/METTL3 Axis in Cheng’s research." (PMID 36870954, 2023). "Taken together, our results suggest that phospho-ATM may be a primary mediator of CTL invasion in numerous C-class tumors such breast, pancreatic, and gastric cancers." (PMID 29615613, 2018). "MET, ATM, FGFR2, and HER2 were profiled on gastric cancer biopsy samples." (PMID 26587992, 2015). "Moreover, significant negative correlation was also observed between ATM methylation and expression in gastric cancer samples (Cor = -0.17, FDR = 1.2e-03)." (PMID 40652278, 2025). "However, in the phase III GOLD trial, adding PARP inhibitor olaparib to second-line paclitaxel treatment in patients with advanced gastric cancer showed no statistically significant improvement in OS in the whole study population or in the ATM-negative subgroup." (PMID 37370858, 2023).
Fanconi anemia (81 papers, 2004 to 2026). Fanconi anemia (FA) is a hereditary DNA repair disorder characterized by progressive pancytopenia with bone marrow failure, variable congenital malformations and predisposition to develop hematological or solid tumors. "FANCD2 is a key factor in the Fanconi anemia pathway, and its function depends on the activation of Ataxia telangiectasia mutated (ATM)/Chk2 signaling." (PMID 40725100, 2025). "Most detected variants affected the Fanconi anemia/DNA repair pathway (34%, ATM, FANCA, FANCI, MLH1, MSH6, POLE, RAD51C, RAD51D) followed by mutations altering the SWI/SNF (SWItch/sucrose non-fermentable) complex (22%, ARID1A and SMARCA4)." (PMID 34200508, 2021). "Several DNA repair pathways, such as ataxia-telangiectasia-mutated (ATM), Fanconi anemia (FA), nucleotide excision repair (NER) pathways, are activated in response to platinum-induced DNA damage." (PMID 26964739, 2016). "We previously demonstrated that Fanconi Anemia (FA) pathway deficient tumor cells are hypersensitive to inhibition of the Ataxia Telangiectasia Mutated (ATM) kinase." (PMID 19371427, 2009). "Examples include BRIP1, PALB2, and ataxia-telangiectasia mutated (ATM) variant alleles that produce a Fanconi anemia (BRIP1 and PALB2) or ATM phenotype when inherited in biallelic fashion, but result in only moderate cancer susceptibility as a single deleterious allele." (PMID 30120226, 2018). "Recent studies have shown that the disruption of any HR-related pathway, such as by BRCA mutations, and disruption of Fanconi anemia, and ATM genes, can predict the sensitivity of tumors to the inhibition of PARP1 by small-molecule inhibitors and the associated cytotoxicity." (PMID 28820388, 2017). "Notably, patients with ATM/ATR pathogenic genetic alterations were likely to be accompanied by mutations in Fanconi anemia (FA) and homologous recombination (HR) pathways, which were confirmed using both the study (P < 0.001) and validation (P < 0.001) cohorts." (PMID 38041093, 2023). "Studies have shown that mTOR inhibitors, such as AZD8055, can downregulate FANCD2 expression, reduce ATM/Chk2 activity, and weaken the repair capacity of the Fanconi anemia pathway, thereby exacerbating DNA damage accumulation." (PMID 40725100, 2025). "The Cancer Genome Atlas (TCGA) analysis reported that HGSC tumors are characterized by mutations in PTEN (7%), RAD51C (3%), ATM/ATR (2%) and Fanconi anemia genes (5%)." (PMID 36531003, 2022). "HRD is an emerging biomarker defined by the mutations of BRCA1/2 genes, along with other Fanconi anemia pathway genes (RAD51D, NBN, and ATM)." (PMID 35983074, 2022). "In GSEA analysis, several pathways were significantly enriched corresponding to the E2F2 high expression phenotype, including ATR pathway, ATM signalling pathway, mismatch repair, base excision repair, homologous recomibination and Fanconi Anemia pathway." (PMID 35069909, 2022). "Several signal pathways were significantly enriched in high E2F2 expression group, including ATR pathway, ATM signalling pathway, mismatch repair, base excision repair, homologous recomibination and Fanconi Anemia pathway." (PMID 35069909, 2022). "Similar results have since been observed with mutations in other DNA repair proteins, including ataxia telangiectasia mutated (ATM) and members of the Fanconi anemia pathway." (PMID 34945003, 2021).
Fanconi anemia (continued). "The Fanconi anemia (FA) pathway cross talks with the ATM and ATR pathways in cell cycle control and the repair of DNA interstrand cross-links." (PMID 28196964, 2017). "In this study, 88% of patients with alteration of DNA repair genes (BRCA1&2, ATM, Fanconi anemia genes) had an objective response." (PMID 28978184, 2017). "The Fanconi anemia (FA) pathway is a part of the DNA damage response and mediates cross talk between the ATM and ATR pathways." (PMID 28196964, 2017). "Appropriate prenatal counseling and partner testing is advised in situations involving mutations in genes that carry a recessive disease risk (those in the Fanconi anemia pathway, NBN, ATM, etc.)." (PMID 26484312, 2015). "Another indirect evidence of a potential verification comes from the lethal effect of ATM gene deletion in defective Fanconi anemia (FA) pathway cells." (PMID 20015360, 2009). "Additionally, significant roles are played by PALB2, ATM, ATR, CHEK1, CHEK2, RAD51, and genes linked to Fanconi anaemia." (PMID 40069561, 2025). "There are numerous genes involved in the DDR pathway, and several studies suggest that platinum therapy may benefit patients with mutations in genes such as ATM and ATR, those within the MRN complex (e.g., RAD50), and Fanconi anemia core genes." (PMID 39860372, 2025). "HRD has been observed not only in ovarian cancer patients with germline or somatic BRCA1 or BRCA2 mutations but also in those with epigenetic silencing of BRCA1 or loss of function of other genes, such as ATM, ATR, BARD, BRIP, EMSY, PALB2, RAD51, and Fanconi Anemia Complementation Group genes." (PMID 36836518, 2023). "GSEA disclosed that E2F2 was probably involved in several pathways, including ATR pathway, ATM signalling pathway, mismatch repair, base excision repair, homologous recomibination, Fanconi Anemia pathway, multicancer invasiveness signature, and cancer stem cells." (PMID 35069909, 2022). "Although they mainly affect the BRCA1 and BRCA2 genes, they have been detected in other genes such as RAD51C hypermethylation (RAD51 paralog C), ATM (ataxia telangiectasia mutated serine-protein kinase gene), or ATR mutations, and mutations of the HR interacting Fanconi anemia gene." (PMID 34638899, 2021). "In regard to DNA damage, the ataxia-telangiectasia mutated (ATM), Fanconi anemia E3 monoubiquitin ligase core complexes (FANC transcripts—A/B/E/F/G/M), FANC2, FANCI, BRCA1, BRCA2, RAD51, PALB2, and ATR (ATM- and Rad3-related) genes were among the most affected." (PMID 33322336, 2020). "The gene panel used for the analyses of the DNA of 41 patients by massive sequencing detected the presence of numerous variants in genes coding for proteins involved in DNA repair such as ATM, ATR, BRCA1, BRCA2 and several genes of the FANC complex, mutated in Fanconi Anemia." (PMID 30995915, 2019). "Considerable evidence is now available suggesting that loss of one or several key genes involved in HR, among these ATM, CHEK1/2, NBN, RAD51 and genes of the Fanconi Anemia complementation group, is associated with sensitivity of cancers to platinum drugs and PARP inhibitors." (PMID 27756336, 2016). "In addition to BRCA1/2 deficiency, the amplification of EMSY and deficiencies in PTEN, Fanconi Anemia genes, RAD genes and DNA repair genes involved in HR (including ATM, ATR and CHEK1/2) have also been identified to cause HR defects in human cancer." (PMID 25437005, 2014).